ASS1 (argininosuccinate synthase 1)
Diseases named in the same sentence as ASS1 in open-access papers (continued):
Sharing a sentence is not in itself a finding about the gene and the disease.
sarcoma (18 papers, 2013 to 2025). A usually aggressive malignant neoplasm of the soft tissue or bone. "Some ASS1-deficient sarcomas reportedly exhibit compensatory upregulated serine synthesis and increased sensitivity to PHGDH inhibitors in response to arginine depletion." (PMID 36319669, 2022). "Resistance to doxorubicin, one of the principal chemotherapy agents used in sarcoma treatment, is associated with ASS1 downregulation, suggesting relapsed sarcomas are more likely to be arginine auxotrophic." (PMID 28969007, 2017). "The arginine auxotrophy, because of ASS1 loss in sarcomas, immediately points to the use of arginine depletion as a potentially effective therapeutic strategy." (PMID 27735949, 2016). "We also demonstrate that, unlike many other tumors where ADI-PEG20 treatment alone is sufficient to induce cell death, arginine deprivation in sarcoma cell lines deficient in ASS1 produces a prolonged starvation." (PMID 27735949, 2016). "In this context, our finding of a near universal ASS1 loss provides the first druggable genetic alteration in sarcoma that encompasses all histologies." (PMID 27735949, 2016). "We now show that sarcoma as a disease is characterized by arginine auxotrophy owing to the loss of ASS1 expression." (PMID 27735949, 2016). "The use of a pegylated arginine deiminase (ADI-PEG20) to pharmacologically deplete exogenous arginine in sarcoma cells (typically ASS1 deficient cells) resulted in prolonged arginine starvation and metabolic stress and had already been tried with promising growth restraining effects." (PMID 36232732, 2022). "Concomitantly, GLS inhibition could also explore a potential synthetical lethality effect on ASS1-deficient sarcomas and is currently being studied in GIST and NF-1 mutated cancers." (PMID 36232732, 2022). "Argininosuccinate synthetase 1 (ASS1) silencing in carcinomas and sarcomas leads to a dependence on extracellular arginine for survival." (PMID 39898973, 2025). "In a study of 708 sarcoma tumor samples, argininosuccinate synthase 1 (ASS1) expression was lost in 87%." (PMID 36969049, 2023). "As previously discussed, preclinical studies showed that ~90% of sarcomas have low expression of ASS1, making these cells more dependent on extracellular sources of arginine." (PMID 36276057, 2022). "Arginine auxotrophy can result from the silencing of ASS1 in several tumor types, including sarcomas." (PMID 36276057, 2022). "Arginine auxotrophy due to the silencing of argininosuccinate synthetase 1 (ASS1) occurs in many carcinomas and in the majority of sarcomas." (PMID 32814773, 2020). "Our observation is in contrast to previous pilot studies in sarcoma showing that only a subset of tumors exhibited reduced ASS1 expression." (PMID 27735949, 2016). "Consistent with the high degree of ASS1 negativity in primary sarcomas, 86.7% of the cell lines (13/15) exhibited minimal ASS1 expression (see normalized expression levels)." (PMID 27735949, 2016). "Further work to fully understand the nature of ASS1 silencing in sarcomas is ongoing." (PMID 35582579, 2019). "The high incidence of ASS1 silencing in sarcoma may be a consequence of its tissues of origin, but this is a subject of ongoing research." (PMID 35582579, 2019). "Together, these data suggest that treatment of sarcoma cells with ADI-PEG20 may induce a prolonged state of starvation before re-expression of ASS1." (PMID 27735949, 2016). "Therefore, compared with other tumors where ASS1 expression levels were observed along a continuum, results from our analyses indicate that sarcomas as a class are almost uniformly ASS1 negative or highly deficient." (PMID 27735949, 2016). "Because MTAP is linked to polyamine metabolism and adenine and methionine salvage, examining whether MTAP inactivation promotes angiogenesis by perturbing the metabolic balance of sarcoma cells is conceivable, similar to the scenario involved in deregulated ASS1." (PMID 25426549, 2014).
sarcoma (continued). "Dual treatment with ADI-PEG20 and A1331852 increased the percentage of cell death in cell lines originating from sarcomas with no or little ASS1 expression, such as RH28, SKUT1, LUPI, HTB93, and HT1080." (PMID 39898973, 2025). "In the case of sarcomas, a 2016 study found that almost 90% of sarcoma tumors have low ASS1 expression; however, ASS1 promoter methylation is not observed in sarcomas." (PMID 36276057, 2022). "In each of the resistant tumors, ASS1 re-induction was clearly detected, suggesting that ADI-PEG20 treatment of sarcomas could ultimately fail because of re-expression of ASS1." (PMID 27735949, 2016). "Not surprisingly, ASS1 expression levels correlated with ADI-PEG20 IC50 values among our panel of sarcoma cell lines (R2=0.95, 95% CI: 0.89–0.99; P<0.001)." (PMID 27735949, 2016). "In a search for common metabolic targets in sarcomas, we profiled over 700 specimens across 45 of the most common subtypes and observed a striking absence of ASS1 in ~90% of these tumors irrespective of histology." (PMID 27735949, 2016). "To determine which of these fates occurred in the case of sarcoma, we performed an in vivo xenograft tumor experiment using the SK-LMS-1 cell line and measured the effects of ADI-PEG20 exposure (see Materials and methods section) on tumor growth and ASS1 expression." (PMID 27735949, 2016). "Thus, unlike other cancer cell lines deficient in ASS1 expression where treatment with ADI-PEG20 is lethal, exploitation of arginine auxotrophy by ADI-PEG20 in sarcoma cell lines results in cytostasis instead." (PMID 27735949, 2016). "Immunohistochemical analysis of sarcomas shows they may have reduced or absent ASS1 expression." (PMID 28969007, 2017).
colorectal cancer (17 papers, 2016 to 2026). A primary or metastatic malignant neoplasm that affects the colon or rectum. "Next, we measured ASS1 mRNA and ASS1 protein expression in human colorectal cancer cell lines with a known mutational profile, as performed previously by others." (PMID 34599156, 2021). "While the role of ASS1 in cancer as well as the molecular mechanism mediating ASS1 upregulation remains unclear, it has been described that high ASS1 expression is associated with increased proliferation and tumourigenicity of colorectal cancer." (PMID 33809510, 2021). "Colorectal cancer cells frequently suppress the expression of argininosuccinate synthetase 1 (ASS1), rendering them dependent on extracellular arginine." (PMID 41827707, 2026). "Studies have shown that elevated ASS1 expression promotes intestinal epithelial cell regeneration, yet its role in colorectal cancer initiation and progression remains controversial." (PMID 41488637, 2025). "While this study establishes a pivotal role for ZFPL1 in promoting colorectal cancer progression and metastasis through ASS1 stabilization, urea cycle reprogramming, and immunomodulation, several limitations remain to be addressed." (PMID 41216870, 2025). "This upregulated expression of ASS1 in specific cancers, including colorectal cancer, suggests its potential role as a target for therapeutic interventions." (PMID 38338444, 2024). "Inhibition of ASS1 can reduce proliferation of breast or colorectal cancer and moderately affected BAP1-altered MPM cells expressing ASS1, consistent with the idea that ASS1 can support MPM cell survival." (PMID 36669126, 2023). "Recent reports suggest a role for increased ASS1 expression in the growth and survival of colorectal cancer cells." (PMID 34599156, 2021). "A recent report has shown that some colorectal cancer cell lines have low ASS1 and OTC expression, which renders these cell lines arginine auxotrophic (dependant on extracellular arginine), similar to our Apc-Ass1 knockout model." (PMID 34599156, 2021). "This study shows that in a xenotransplantation model, arginine deprivation leads to inhibition of proliferation of the ASS1-low colorectal cancer cells." (PMID 34599156, 2021). "In contrast, other types of cancer, such as colorectal cancer, show an increase in the expression of ASS1." (PMID 34599156, 2021). "Here we investigated the function of ASS1 in the gut epithelium during tissue regeneration and tumorigenesis, using intestinal epithelial conditional Ass1 knockout mice and organoids, and tissue specimens from colorectal cancer patients." (PMID 34599156, 2021). "It has been suggested that knockdown or inhibition of Ass1 reduces fumarate levels, which leads to inhibition of growth in colorectal cancer cell lines." (PMID 34599156, 2021). "ASS1 has been suggested as an upregulated target for primary human colorectal tumors, whose inhibition or genetic ablation potentially allows colorectal cancer pathogenicity." (PMID 32850805, 2020). "Amongst others, human colorectal cancer (CRC) falls into the ASS1-positive category due to the high ASS1 protein level detected in the majority of CRC tissue samples in early studies." (PMID 27689335, 2016). "Notably, ASS1 exhibits overexpression in various cancer types, contributing to the enhanced proliferation of human colorectal cancer cells." (PMID 38338444, 2024). "Interestingly, ASS1 is a metabolic regulator of colorectal cancer pathogenesis, although the inhibitor used in the study was an shRNA, which opens new ways for ASS1 molecule inhibitors." (PMID 35054460, 2022). "A similar effect may be the reason for the high effectiveness of arginine in colorectal cancer, as both of these neoplasms show high expression levels of argininosuccinate synthase (ASS1)." (PMID 33809994, 2021).
colorectal cancer (continued). "However, the efficacy of the proposed combination in the presence of extracellular citrulline, the substrate for arginine synthesis by ASS1, remains to be elucidated, in particular for malignant cells with positive and/or inducible ASS1 as in colorectal cancer (CRC)." (PMID 27689335, 2016). "Based on the differential transcriptional expression analyses of colorectal cancer (CRC) tumors, urea cycle enzymes including ASS1 has been identified to be transcriptionally upregulated in KRAS-mutant primary CRC." (PMID 35910381, 2022). "Here, we show that colorectal cancers (CRCs) display negligible expression of OTC and, in subset of cases, ASS1 proteins." (PMID 30108309, 2018). "An important consequence of this finding is that our data suggest that epithelial ASS1 may not be a potential therapeutic target for colorectal cancer treatment." (PMID 34599156, 2021). "In colorectal cancer, Snail mediates tumor cell metastasis by preventing non-coding RNA LOC113230-induced degradation of ASS1." (PMID 35910381, 2022).
gastric cancer (16 papers, 2015 to 2025). A primary or metastatic malignant neoplasm involving the stomach. "We thushypothesized that the expression of ASS1 in gastric cancer is associated with poorprognosis." (PMID 25928182, 2015). "Here, knockdown of ASS1 significantly inhibited the proliferation, colony formation, and migration/invasion of gastric cancer cells, and promoted apoptosis." (PMID 38172873, 2024). "We found that ASS1 expression was significantly upregulated in gastric cancer samples compared to normal samples (p < 0.001)." (PMID 38172873, 2024). "To further understand the involvement of abnormal arginine metabolism in gastric cancer, we examined the role of ASS1, a key rate-limiting enzyme in this pathway, in gastric cancer cells." (PMID 38172873, 2024). "Knockdown of the key rate-limiting enzyme argininosuccinate synthetase 1 (ASS1) of the arginine synthesis pathway was found to inhibit colony formation, proliferation and migration of gastric cancer cells." (PMID 38172873, 2024). "Western blot analysis revealed that ASS1 expression levels were higher in the gastric cancer cell lines, MKN28 and HGC-27." (PMID 38172873, 2024). "The high expression level of ASS1 in gastric cancer has been reported, suggesting the important role of ASS1 in the metabolic process of gastric cancer." (PMID 35265615, 2022). "Arginine epigenetically modulates the WNT/β-catenin pathway and ASS1 promotes gastric cancer cell invasion through β-catenin stabilization." (PMID 35717443, 2022). "For example, the expression of ASS1 in gastric cancer can promote the invasion of cancer cells, resulting in poor prognosis in patients with gastric cancer." (PMID 35898872, 2022). "A previous study proved that ASS1 is expressed in human gastric cancer cell lines and its suppression efficiently hinders gastric cancer cell lines metastatic capabilities in vitro and in vivo." (PMID 32390765, 2020). "To further illustrate thecontribution of ASS1 to the migration of gastric cancer cells, we interfered withits functioning using shRNA." (PMID 25928182, 2015). "To study the effect of ASS1 on human gastric cancer cells, we usedvector-mediated short hairpin RNA (shRNA) to silence ASS1 expression in theMKN45 human gastric cancer cell line." (PMID 25928182, 2015). "Experiments using a 3IB2 murine gastric cancer modelfurther supported the notion that ASS1 is essential for metastasis." (PMID 25928182, 2015). "Further studies are needed to investigate the proteinexpression of OCT and ASS1 in gastric cancer specimens and their effects on argininedeprivation therapy." (PMID 25928182, 2015). "In the current study, we first determined the expression of ASS1 in humanand murine gastric cancer cell lines and found that these cells displayed highprotein levels of both ASS1 and STAT3." (PMID 25928182, 2015). "To examine the possible roles of Ass1 in murine gastric cancer cells, we knockeddown the expression of Ass1 using shRNA." (PMID 25928182, 2015). "For the study of long-term ASS1 function in gastric cancer, weestablished four stable cell lines expressing two different RNAi constructs,RNAi-1.1, RNAi-1.2, RNAi-2.1, and RNAi-2.2." (PMID 25928182, 2015). "We then determined the effects of Ass1 downregulation on themigration of murine gastric cancer cells." (PMID 25928182, 2015). "Theseresults suggest that the silencing of Ass1 expression reduces STAT3 expressionin human gastric cancer cell lines." (PMID 25928182, 2015). "We suggest that ASS1 suppression in gastric cancerprovides a survival advantage to gastric cancer patients receiving pegylatedarginine deiminase treatment." (PMID 25928182, 2015). "We detected the protein expression of ASS1 in human gastric cancer celllines (AGS, NCI-N87, and MKN45) and in murine gastric cancer cell lines (3I and3IB2)." (PMID 25928182, 2015). "Taken together, thedownregulation of ASS1 expression in gastric cancer cells inhibited cell motilityand altered cell sensitivity to arginine deprivation." (PMID 25928182, 2015).
gastric cancer (continued). "Taken together, these results indicate that Ass1 plays asignificant role in the metastasis of mouse gastric cancer cells." (PMID 25928182, 2015). "Finally, we found that knockdown of ASS1 significantly inhibited the proliferation, colony formation, and migration of gastric cancer cells, and promoted apoptosis, further supporting a cancer-promoting role for ASS1 in gastric cancer." (PMID 38172873, 2024). "To determine whether abnormal expression of ASS1 contributed to poor patient prognosis in middle third gastric cancer, we analyzed 197 gastric cancer samples based on their stomach location data, as well as 32 normal tissue samples from the TCGA database." (PMID 38172873, 2024). "Interestingly, we found that ASS1 levels were significantly increased in gastric cancer tissues with a more pronounced elevation observed in middle third gastric cancer." (PMID 38172873, 2024). "Furthermore, ASS1 was found to be upregulated in the middle third gastric cancer samples compared to samples from other locations (p = 0.059)." (PMID 38172873, 2024). "However, a previous study reported that ASS1 is highly expressed and is positively related to the aggressiveness and worse prognosis of gastric cancer." (PMID 35674458, 2022). "Downregulation of ASL is of clinical relevance as, if confirmed on a larger set of samples, it implies that gastric cancer, particularly the one located in cardia, might still be sensitive to arginine-deprivation therapies, despite ASS1 overexpression." (PMID 34439753, 2021). "In addition, inhibition of ASS1 expression in combination with arginine depletion in gastric cancer has been shown to inhibit cancer cell migration and motility, therefore affecting metastasis formation in vivo." (PMID 33809510, 2021). "Moreover, this study indicated that when the levels of arginine drops, and it is accompanied with silencing the expression of ASS1, gastric cancer cell lines migration capability got hindered." (PMID 32390765, 2020). "Theseresults confirmed the expression of ASS1 in gastric cancer cell lines." (PMID 25928182, 2015). "We next investigated whether there is a correlation between Ass1 expression andthe migration potential of gastric cancer cells." (PMID 25928182, 2015). "We further demonstrated theeffects of ASS1 on gastric cancer cell migration and metastasis." (PMID 25928182, 2015). "Therefore, the silencing of ASS1 expression andarginine restriction reduce tumor motility in human gastric cancer." (PMID 25928182, 2015). "We further determined whetherthe downregulation of Ass1 affected cell growth in a murine gastric cancer cellline." (PMID 25928182, 2015). "However, ASS1 also has oncogenic potential in gastric cancer and hepatocellular adenoma." (PMID 34447409, 2021). "Additionally, ASS1 may contribute to the metastasis of gastric cancer." (PMID 39991825, 2025). "Taken together,ASS1 regulates STAT3 signaling and plays an important role in the liver metastasisof gastric cancer." (PMID 25928182, 2015). "Thesilencing of ASS1 expression in MKN45 and 3IB2 gastric cancer cells markedlydecreased STAT3 protein expression." (PMID 25928182, 2015). "Among the top 10 DRGs for Chinese (GSE54129), six genes have been reported to be gastric cancer (GC) related (REG4, ANXA13, C7, ASS1, MSMB, CREB1) and the rest four were directly regulated by known gastric cancer genes in our GRNs, in which two genes are also cancer related (BPTF, CLCA1)." (PMID 29745833, 2018). "Thus, Ass1 downregulation orinhibition did not affect gastric cancer cell growth." (PMID 25928182, 2015).